RNU6-504P (RNA, U6 small nuclear 504, pseudogene)
Gene: Small nuclear RNA gene on chromosome X (51,870,706 to 51,870,809, reverse strand). Ensembl gene ENSG00000252377.
Homologues: Orthologues: chimpanzee U6 (99% identical), macaque U6 (93% identical), dog U6 (73% identical), pig U6 (73% identical). Paralogues in human: RNU6-1018P (94% identical), RNU6-1209P (83% identical), RNU6-797P (83% identical), RNU6-1287P (81% identical), RNU6-500P (81% identical), RNU6-838P (81% identical), RNU6-1083P (80% identical), RNU6-1145P (80% identical), RNU6-115P (80% identical), RNU6-1332P (80% identical), RNU6-188P (80% identical), RNU6-424P (80% identical), and 1289 more.